HTR2A (5-hydroxytryptamine receptor 2A)
Diseases named in the same sentence as HTR2A in open-access papers (continued):
Sharing a sentence is not in itself a finding about the gene and the disease.
cognitive deficits (9 papers, 2005 to 2024). "The genes of cognitive impairment regulated by non-coding RNAs include GRIN2A, BDNF, HTR2A, and NMDAR." (PMID 36406755, 2022).
Stroke (8 papers, 2010 to 2025). Sudden impairment of blood flow to a part of the brain due to occlusion or rupture of an artery to the brain. "Htr2a, a gene heavily implicated in the post-stroke depression and Kcnj4 (excitatory neurotransmission) were also persistently upregulated in young rats." (PMID 23251410, 2012). "In this study, an RNA-seq analysis revealed the hub gene, Htr2a, a gene encoding the serotonin receptor subtype 5-HT2A receptor, to be differentially expressed in the DCN in post-stroke animals receiving EE." (PMID 31164998, 2019). "Eight common genes were found across all three compounds and stroke: MAPK1, PRKCB, PRKCG, HDAC1, HTR1A, HTR2A, HTR2C, and HTR7." (PMID 41011194, 2025).
autism (7 papers, 2014 to 2025). Persistent deficits in social interaction and communication and interaction as well as a markedly restricted repertoire of activity and interest as well as repetitive patterns of behavior. "Recently, an altered methylation status in the placental serotonin receptor gene HTR2A has been shown to be associated with neurobehavioral outcomes and autism in infants, although the intrinsic role of HTR2A in neurodevelopment has not been clearly elucidated." (PMID 28538662, 2017).
glioma (7 papers, 2015 to 2025). A benign or malignant brain and spinal cord tumor that arises from glial cells (astrocytes, oligodendrocytes, ependymal cells). "In glioma, HTR2A expression is associated with tumor heterogeneity and immune cell infiltration, potentially influencing patient prognosis and the effectiveness of immunotherapies." (PMID 41331166, 2025). "HTR2A has also been confirmed to be associated with glioma grade through neuroactive ligand receptor interaction." (PMID 36980973, 2023). "Previous studies have shown that HTR2A expression is associated with low-grade and high-grade gliomas through neuroactive ligand receptors." (PMID 37564635, 2023). "Additionally, HTR2A has been implicated in neuroactive ligand–receptor interactions and calcium signaling pathways, which may play roles in glioma pathogenesis." (PMID 41331166, 2025). "Metabotropic glutamate receptor 1 (GRM1), 5-Hydroxytryptamine (serotonin) receptor 7 (HTR7), and 5-Hydroxytryptamine (5-HT) receptor 2A (HTR2A) may play a role in glioma by participating in the interaction pathway of neuroactive ligand receptor interaction pathway." (PMID 36980973, 2023). "Thus, the present results suggested that HTR2A might play an important role in gliomas via neuroactive ligand–receptor interactions, which was consistent with previous findings." (PMID 30124166, 2018). "MCOLN2, TRPV4, and ITPR2 were significantly highly expressed in glioma tissues, and the three most significantly down-regulated genes (PRKCG, CAMK2A, and HTR2A) had lower expression in tumor tissues." (PMID 41331166, 2025). "Specially, the present study used real-time PCR to verify the expression of key genes GRM2, GRM7, HTR2A and TFAP2C through human glioma cell line U251." (PMID 30124166, 2018). "A recent study discovered that upregulation of HTR2A, which is a target in inflammatory mediator regulation of Transient Receptor Potential (TRP) channels, and COMT was significantly positively correlated with glioma carcinogenesis." (PMID 38003496, 2023).
Alzheimer disease (6 papers, 2013 to 2024). A progressive, neurodegenerative disease characterized by loss of function and death of nerve cells in several areas of the brain leading to loss of cognitive function such as memory and language. "Previous studies showed that the neuroprotective benefits of 17β-estradiol (E2) ameliorated cholinergic deficit, elevated the expression levels of choline acetyltransferase and 5-hydroxytryptamine receptor 2A, and lowered the expression of GFAP in a rat model of Alzheimer’s disease induced by OVX." (PMID 38732143, 2024).
asthma (6 papers, 2012 to 2024). "Clinical studies with inhibitors of individual HTRs such as HTR1A or HTR2A have had only a small benefit for asthma, but this may reflect involvement of multiple HTRs during asthma." (PMID 38845678, 2024). "However, we know that such associations of HTR2A, HTR2C, and MAOB gene polymorphisms with asthma phenotypes have not yet been investigated." (PMID 37238670, 2023).
bipolar depression (6 papers, 2017 to 2025). "Supporting a developmental origin of these changes, several linkage studies have described an association between bipolar disorder and single nucleotide polymorphisms in genes such as TPH2, HTR1A, HTR2A, HTR2C or SLC6A450–55." (PMID 30087403, 2018). "While HTR1A, HTR2A, and HTR7 are known targets of lurasidone, MAOB, HTR3A, SLC18A2, and HTR1B were identified for the first time as targets of lurasidone potentially involved in its associated induction of acute manic episodes in people with bipolar depression." (PMID 40202273, 2025). "Our bioinformatics and computational analyses demonstrated that lurasidone may regulate the serotonergic synapse signaling pathway by targeting proteins such as MAOB, HTR1A, HTR2A, HTR3A, SLC18A2, HTR1B, and HTR7 to induce treatment‐emergent mania in people with bipolar depression." (PMID 40202273, 2025). "HTR2A and HTR1B exhibited the highest binding affinities among the seven target proteins, suggesting that these proteins may be the ones largely responsible for lurasidone‐induced treatment‐emergent mania in people with bipolar depression." (PMID 40202273, 2025). "This study revealed that lurasidone may regulate the serotonergic synapse signaling pathway by interacting with the identified core targets MAOB, HTR1A, HTR2A, HTR3A, SLC18A2, HTR1B, and HTR7 to induce treatment‐emergent mania in people with bipolar depression." (PMID 40202273, 2025).
melanoma (6 papers, 2010 to 2025). A malignant, usually aggressive tumor composed of atypical, neoplastic melanocytes. "HTR2A is more commonly investigated in association with SSRI response; however, it was also shown that HTR2A has a role in melanogenesis in melanoma cells and zebrafish." (PMID 39337694, 2024). "The 5-HT2A serotonin receptor (HTR2A) has been reported to be involved in the serotonin- or serotonin receptor 2A agonist-induced melanogenesis in human melanoma cells." (PMID 35682806, 2022). "We demonstrated that HTR2A antagonists (AT1015 and ketanserin) attenuated the melanogenesis induction of serotonin in both mouse melanoma cells and zebrafish embryos." (PMID 35682806, 2022). "In this research, cultured mouse melanoma cell line B16F10, human skin, and zebrafish embryos were used to elucidate the downstream signaling of HTR2A in regulating melanogenesis and to verify the potential application of HTR2A in the treatment of pigment-associated cutaneous diseases." (PMID 35682806, 2022).
mental disorder (6 papers, 2011 to 2025). A disease that has its basis in the disruption of mental process. "Conducted on a cohort of 221 patients with treatment-resistant mental disorders, the research focused on DRD2 and HTR2A gene variants-specifically, rs1801028, rs6314, rs7997012, and rs6311." (PMID 39934320, 2025). "HTR1A and HTR2A have also been studied in relation to mental disorders." (PMID 21448266, 2011). "In our results, therapeutic targets or biomarkers of neurological disorder and mental disorder, such as DRD1, DRD2, DRD4, HTR2A, PRL and ADRA2A, were assigned with high scores in both mirtazapine and pramipexole." (PMID 29371651, 2018).
steatosis (5 papers, 2018 to 2026). Increased lipid within the cytoplasm of cells. "We demonstrate that autonomic nerve signals from livers exposed to CDAA and HFD-induced fatty changes activate 5-HT secretion into the serum from the SI, which then acts on HTR2A on the hepatocytes that is involved in steatosis in NAFLD." (PMID 35765850, 2022). "Interestingly, gene sets which contribute to inflammation and fibrosis in nonalcoholic steatohepatitis pathogenesis as well as gene sets that contribute to steatosis were significantly less enriched in Htr2a LKO mice 31–40." (PMID 30446669, 2018). "It has also been seen that inhibition of HTR2A and HTR2B reduces proliferation, increases serotonin-induced apoptosis and can attenuate steatosis and fibrosis." (PMID 33081272, 2020).
breast carcinoma (4 papers, 2009 to 2025). "In summary, our study not only provides a novel risk signature for prognosis prediction of breast cancer based on HTRs, but also highlights the activation of HTR2A as a novel therapeutic strategy to improve breast cancer prognosis via mobilizing CD8+T cells." (PMID 37795441, 2023). "Zebrafish and mouse breast cancer xenografts were used to determine the effect of HTR2A/2B inhibitor on breast cancer metastasis." (PMID 37795441, 2023). "To explore the potential mechanisms of HTR2A and HTR2B as prognostic biomarkers for breast cancer, we analyzed the association between these two HTR receptors and immune cell infiltration in the tumor microenvironment through the TIMER database." (PMID 37795441, 2023). "The expression levels of HTR1A, HTR1B, HTR2A, HTR2B, HTR2C, HTR4, and HTR7 were significantly downregulated in highly malignant breast cancer types." (PMID 37795441, 2023). "However, when compared to normal breast tissue, HTR1A, HTR1B, HTR2A, HTR2B, HTR2C, HTR4, and HTR7 were suppressed in high malignancy breast cancer types, whereas they were highly expressed in low malignant breast cancer." (PMID 37795441, 2023). "Therefore, it was hypothesized that low expression of HTR2A and HTR2B inhibits the activation of CD8+ T cells, and subsequently promotes breast cancer invasion and leads to poor prognosis of breast cancer patients." (PMID 37795441, 2023). "Furthermore, inhibition of HTR2A expression could suppress CD8+ T cell proliferation and enhance invasion and metastasis of breast cancer cells in both zebrafish and mice model." (PMID 37795441, 2023).
cardiac hypertrophy (4 papers, 2021 to 2025). "Accumulating evidence indicates HTR2A engages pro-hypertrophic signalling via the PI3K–PDK1–AKT–mTOR pathway in an isoproterenol (ISO)–induced mouse model of cardiac hypertrophy." (PMID 41468376, 2025). "Also, it has been clarified that the overexpression of 5-hydroxytryptamine receptor 2A was involved in cardiac hypertrophy through the AKT/mTOR signaling pathway." (PMID 36742144, 2023). "Furthermore, we demonstrated that 5-hydroxytryptamine receptor 2A (HTR2A) fosters the development of cardiac hypertrophy by activating PI3K-PDK1-AKT-mTOR signaling." (PMID 34059001, 2021). "Moreover, it has been demonstrated that HTR2A is upregulated in cardiac muscle and cardiomyocytes isolated from the left ventricle of rats subjected to transverse aortic banding, a model of pressure-overload-induced cardiac hypertrophy." (PMID 41468376, 2025). "Further investigation into the roles of miR-34a, miR-351, and miR-490*, alongside validated genes such as HTR2A, SGPP1, ITGA7, and GANC is essential to elucidate their contributions to early-onset cardiac hypertrophy." (PMID 41468376, 2025).
Hyperglycemia (4 papers, 2016 to 2020). An increased concentration of glucose in the blood. "In the present study, we hypothesized that increases in hepatic FGF21 expression and circulating FGF21 levels precede diet-induced insulin resistance and hyperglycemia, which may be related to the increased expression of hepatic htr2a and Sdf2l1." (PMID 32978487, 2020). "In summary, the present findings suggest that expression of the hepatic htr2b is increased in young diabetic db/db mice and KKAy mice, and pharmacologic inhibition of htr2b ameliorates the hyperglycemia and altered expression of hepatic FGF21, Sdf2l1 and htr2a in these mice." (PMID 33364514, 2020).
nicotine addiction (4 papers, 2011 to 2025). "A few studies have explored the association of SNPs in the 5-hydroxytryptamine receptor 2A (HTR2A) gene with nicotine addiction." (PMID 28103253, 2017). "The aim of this study was to identify the genetic variants in the DRD4 and HTR2A genes that are associated with cigarette smoking and a higher degree of nicotine addiction in the Mexican Mestizo population." (PMID 28103253, 2017). "HTR2A is also involved in nicotine dependence, as nicotine enhances and elevates the released serotonin." (PMID 39731452, 2025). "Previously, we had reported other SNPs in smoking-related genes as NRXN1, DRD4, HTR2A, CHRNA3, CHRNA5, and CYP2A6 in Mexican mestizo, focused on smokers enrolled in a smoking cessation program, mostly with high tobacco consumption and nicotine dependence." (PMID 34205269, 2021).
bruxism (3 papers, 2014 to 2020). Excessive clenching of the jaw and grinding of the teeth. "Motivated by the evidence of a genetic component to bruxism, association studies with common genetic variants have been conducted, suggesting an association exists between genes and bruxism (dopamine receptor D genes DRD2, DRD3, DRD5, and the 5-hydroxytryptamine receptor 2A gene, HTR2A)." (PMID 32471213, 2020).
fibromyalgia (3 papers, 2005 to 2024). A chronic disorder of unknown etiology characterized by pain, stiffness, and tenderness in the muscles of neck, shoulders, back, hips, arms, and legs. "Research has shown the associations between being susceptible to chronic pain conditions (e.g., chronic widespread pain and fibromyalgia) and serotonin receptor 2A (HTR2A) gene polymorphisms." (PMID 32967120, 2020).
liver diseases (3 papers, 2020 to 2024). "Among the various subtypes of HTRs expressed by hepatocytes, HTR2A and HTR2B show a strong relationship to liver diseases as they transduce the 5-HT signal from the SI via the portal vein." (PMID 35765850, 2022).
memory impairment (3 papers, 2012 to 2021). "Moreover, converging evidence showed that the administration of Htr2c/Htr2a agonists led to short-term memory and long-term memory impairment." (PMID 22359574, 2012).
metabolic syndrome (3 papers, 2013 to 2020). A cluster of metabolic risk factors for CARDIOVASCULAR DISEASES and TYPE 2 DIABETES MELLITUS. "Recent studies suggest that polymorphic variation in the HTR2A gene may be associated with abdominal obesity and the metabolic syndrome, and that HTR2A may be linked to the stability of the stress-related system (i.e., the serotonin-hypothalamic-pituitary-adrenal system)." (PMID 23554917, 2013). "No previous study has analysed DNA methylation levels of HTR2A gene in a population with metabolic syndrome enrolled in a weight loss treatment." (PMID 24959950, 2014).
alcohol abuse (2 papers, 2009 to 2025). The use of alcoholic beverages to excess, either on individual occasions ("binge drinking") or as a regular practice. "Furthermore, HTR2A rs6313, which regulates the expression rate of HTR2A, was found to be associated with alcohol abuse in male patients." (PMID 19742166, 2009).
Dravet syndrome (2 papers, 2021 to 2022). "These ASD genes included the Dravet syndrome gene SCN1A and the Timothy syndrome gene CACNA1C, but also GRIN2B, HTR2A, PCDH9, and other genes." (PMID 34188164, 2021).
glaucoma (2 papers, 2021 to 2024). Increased pressure in the eyeball due to obstruction of the outflow of aqueous humor. "Among the nodes with moderate centrality values, the HTR2A gene (the 5-HT2A receptor) has already been linked to glaucoma." (PMID 39458974, 2024).
hyperhomocysteinemia (2 papers, 2013 to 2021). A serious metabolic condition caused by mutations in the MTHFR gene, medications, or nutritional deficiency. "Likewise, there is some consistent evidence in the heritability of impulse control disorder via Opioid Receptor Kappa 1 (OPRK1), 5-Hydroxytryptamine Receptor 2A (HTR2a) and Dopa decarboxylase (DDC) genotypes, and hyperhomocysteinemia via the Methylenetetrahydrofolate reductase (MTHFR) gene." (PMID 34281267, 2021).
Insulin resistance (2 papers, 2019 to 2020). Increased resistance towards insulin, that is, diminished effectiveness of insulin in reducing blood glucose levels. "Thus, the increased expression of hepatic Sdf2l1 and FGF21 via htr2a might be related to insulin resistance in mice fed a high-fat diet." (PMID 32978487, 2020). "Additionally, different studies have proposed potential DNA methylation biomarkers in relation to plasma insulin levels, insulin secretion and insulin resistance such as those located in PPARGC1A, HTR2A, LY86, TFAM, GIPR, ADIPOQ, and IGFBP3 genes." (PMID 31208038, 2019).
ischemia (2 papers, 2012 to 2018). A hypoperfusion of the BLOOD through an organ or tissue caused by a PATHOLOGIC CONSTRICTION or obstruction of its BLOOD VESSELS, or an absence of BLOOD CIRCULATION. "We hypothesize that MCAO could induce Htr2a and Htr2b overexpression leading to excitability in the early stage of ischemia." (PMID 30533429, 2018).
Myalgia (2 papers, 2021 to 2025). "Another study that stratified participants based on TMDp subtypes investigated polymorphisms in genes encoding serotonin receptors (HTR2A and HTR3A) and found that carriers of the minor allele experienced higher pain intensity in patients with myalgia." (PMID 40868215, 2025). "The distribution of HTR2A (rs9316233), HTR3A (rs1062613), HTR3B (rs1176744), SERT (5-HTTLPR) and COMT (rs4680) genotypes in 117 patients with TMD myalgia (16 men and 101 women)." (PMID 35047998, 2021).
osteoarthritis (2 papers, 2011 to 2024). A noninflammatory degenerative joint disease occurring chiefly in older persons, characterized by degeneration of the articular cartilage, hypertrophy of bone at the margins and changes in the synovial membrane. "miR-214-3p, miR-3120-5p and miR-615-3p, decreased in RA synovial fluid EVs compared with osteoarthritis, were validated to regulate HTR2A expression and mostly released from monocytes." (PMID 38662111, 2024).
osteosarcoma (2 papers, 2019 to 2025). A usually aggressive malignant bone-forming mesenchymal neoplasm, predominantly affecting adolescents and young adults. "We have previously shown that 5HT can act at HTR2A, which are strikingly upregulated in osteosarcoma cells, to influence growth rate." (PMID 30777054, 2019).
rheumatoid arthritis (2 papers, 2016 to 2022). A chronic, systemic autoimmune disorder characterized by inflammation in the synovial membranes and articular surfaces. "In our study, we found signficant hypermethylation of promoter region of HTR2A which indicates the potential clinical diagnostic role in rheumatoid arthritis." (PMID 36561742, 2022). "HTR2A is previously identified as a susceptibility gene for rheumatoid arthritis (RA)." (PMID 36561742, 2022).
viral infection (2 papers, 2019 to 2021). "In addition, CACNA1C and HTR2A‐encoded proteins are involved in viral infections, acting as receptors for influenza virus and JC polyomavirus, respectively." (PMID 34745336, 2021).
alcoholic fatty liver disease (1 paper, 2022). Lipid infiltration of the hepatic parenchymal cells that is due to alcohol abuse. "SAveRUNNER predicted that cyproheptadine, which targets both HRH1 and the serotonin 2A receptor, HTR2A, instead of HRH1 alone would be the best antihistamine for treating non-alcoholic fatty liver disease." (PMID 36313344, 2022).
alexithymia (1 paper, 2024). An agnosia that is a deficiency in understanding, processing, or describing emotions. "The main candidate genes associated with alexithymia are from the serotoninergic pathway (SLC6A4, HTR1A and HTR2A) and neurotransmitter metabolism (DRD2/ANKK1, COMT, BDNF, and OXTR)." (PMID 39202385, 2024). "Therefore, the different contributions of 5HT receptors (HTR1A and HTR2A) in the brain should be considered in alexithymia." (PMID 39202385, 2024).
Arthritis (1 paper, 2024). Inflammation of a joint. "In addition to regulating HTR2A on fibroblast, these miRNAs also contribute to arthritis in other means." (PMID 38662111, 2024).